WWP1 (WW domain containing E3 ubiquitin protein ligase 1)
Description:
E3 ubiquitin-protein ligase which accepts ubiquitin from an E2 ubiquitin-conjugating enzyme in the form of a thioester and then directly transfers the ubiquitin to targeted substrates. Ubiquitinates ERBB4 isoforms JM-A CYT-1 and JM-B CYT-1, KLF2, KLF5 and TP63 and promotes their proteasomal degradation. Ubiquitinates RNF11 without targeting it for degradation. Ubiquitinates and promotes degradation of TGFBR1; the ubiquitination is enhanced by SMAD7. Ubiquitinates SMAD6 and SMAD7. Ubiquitinates and promotes degradation of SMAD2 in response to TGF-beta signaling, which requires interaction with TGIF. Activates the Hippo signaling pathway in response to cell contact inhibition and recruitment to the Crumbs complex at the cell membrane. Monoubiquitinates AMOTL2 which facilitates its interaction with and activation of LATS2. LATS2 then phosphorylates YAP1, excluding it from the nucleus and therefore ultimately represses YAP1-driven transcription of target genes.
Synonyms: AIP5; Tiul1; DKFZP434D2111; hSDRP1
Tractability: Small molecule: a structure with a bound ligand is known; it has a high-quality binding pocket. Antibody: UniProt places it where antibodies can reach, with high confidence; its Gene Ontology location is reachable by antibodies, with medium confidence; the Human Protein Atlas places it where antibodies can reach. PROTAC: UniProt records ubiquitination sites on it; ubiquitination databases record sites on it.
Gene: Protein-coding gene on chromosome 8 (86,342,547 to 86,478,420, forward strand). Ensembl gene ENSG00000123124.
Subcellular location: Cytoplasm; Cell membrane; Nucleus; Cell junction
Subcellular location (Human Protein Atlas): Cytosol; Golgi apparatus; Plasma membrane
Pathways (Reactome):
Gene expression (Transcription): Regulation of RUNX2 expression and activity
Immune System: Antigen processing: Ubiquitination & Proteasome degradation
Signal Transduction: Downregulation of ERBB4 signaling
Transport of small molecules: Stimuli-sensing channels
Gene Ontology:
Molecular function: protein binding; ubiquitin protein ligase activity; ubiquitin-protein transferase activity
Biological process: central nervous system development; monoatomic ion transmembrane transport; negative regulation of DNA-templated transcription; proteasome-mediated ubiquitin-dependent protein catabolic process; protein ubiquitination; symbiont entry into host cell; ubiquitin-dependent protein catabolic process
Cellular component: anchoring junction; cytoplasm; extracellular exosome; plasma membrane; cytosol; nucleus
Genetic constraint (gnomAD): Loss-of-function variants: 42 observed, 116.11 expected, observed/expected ratio (o/e) 0.36, 90% interval 0.28 to 0.47. The upper end of that interval is the gene's LOEUF score, 0.47, which puts it in group 2 of 6, group 1 being the genes least tolerant of losing a copy. Missense variants: 774 observed, 1,070.3 expected, observed/expected ratio (o/e) 0.72, 90% interval 0.68 to 0.77. Synonymous variants: 320 observed, 357.3 expected, observed/expected ratio (o/e) 0.9, 90% interval 0.82 to 0.98.
Homologues: Orthologues: chimpanzee WWP1 (99% identical), macaque WWP1 (98% identical), dog WWP1 (95% identical), pig WWP1 (94% identical), mouse Wwp1 (91% identical), guinea pig WWP1 (90% identical), rat Wwp1 (90% identical), rabbit WWP1 (90% identical), tropical clawed frog wwp1 (76% identical), zebrafish wwp1 (68% identical), Drosophila melanogaster Su(dx) (55% identical), Caenorhabditis elegans wwp-1 (47% identical). Paralogues in human: WWP2 (59% identical), ITCH (58% identical), HUWE1 (36% identical), HECW1 (35% identical), NEDD4L (34% identical), HECW2 (33% identical), NEDD4 (33% identical), SMURF2 (32% identical), SMURF1 (31% identical), HACE1 (25% identical), HECTD1 (21% identical), TRIP12 (21% identical), and 12 more.
Diseases named in the same sentence as WWP1 in open-access papers:
WWP1 is named in the same sentence as 96 diseases in open-access papers, as found by Europe PMC text mining. Sharing a sentence is not in itself a finding about the gene and the disease. The quoted sentences say what the papers report.
breast carcinoma (32 papers, 2012 to 2025). "Knockdown of WWP1 in the breast cancer 184B5 cell line is associated with a decrease of ΔNp63 levels, while knockdown of WWP1 in colorectal HCT116 cells increases TAp63 expression and sensitivity to genotoxic stress." (PMID 27929429, 2016). "Since WWP1 is an oncogene and LATS1 is a tumor suppressor gene in breast cancer, our studies provide a promising therapeutic strategy in which developed drugs targeting WWP1 cause activation of LATS1 in suppressing breast cancer cell growth." (PMID 23573293, 2013). "Conversely, increase of WWP1 expression in breast cancer has been associated with poor prognosis." (PMID 39059493, 2024). "Notably WWP1 is frequently amplified in breast cancer and associated with poor prognosis." (PMID 39059493, 2024). "WWP1, an HECT-type ubiquitin E3-ligase, is frequently amplified and mutated in multiple cancers, including hepatocellular carcinoma and prostate and breast cancers." (PMID 39656237, 2025). "WWP1 also facilitates breast cancer cell tumorigenesis by mediating the degradation of ErbB4, a tumor suppressor in breast cancer." (PMID 40280416, 2025). "WWP1 expression is significantly increased in breast cancer and various other types of cancer, as evidenced by its gene amplification or mRNA overexpression, and high expression of WWP1 predicts poor prognosis." (PMID 39059493, 2024). "For instance, in breast cancer, high WWP1 expression correlates with shorter overall survival (OS) and disease-free survival (DFS)." (PMID 39949609, 2024). "In breast cancer, WWP1 negatively regulates CXCL12-induced CXCR4 lysosomal degradation, thereby facilitating breast cancer cell migration and bone metastasis, leading to poor prognosis (Fig. 5C1,)." (PMID 38129384, 2023). "WWP1 is frequently amplified in ERα (Estrogen receptor α)-positive breast cancer cells resistant to TRAIL (TNF-related apoptosis-inducing ligand)-induced apoptosis." (PMID 38129384, 2023). "Previous studies have shown that WWP1 promotes the proliferation of breast cancer cells by binding and ubiquitinating the LATS1 protein." (PMID 36803368, 2023). "siRNA-mediated inhibition of WWP1 can significantly suppress tumor progression in many cancer types, such as breast cancer, prostate cancer, HCC, oral cancer, gastric cancer, CRC, osteosarcoma, PTC, CSCC, ICC and AML." (PMID 38129384, 2023). "WWP1 is commonly overexpressed and genetically amplified in multiple types of human cancers, such as breast cancer, prostate adenocarcinoma, gastrointestinal cancers, as well as acute myeloid leukemia (AML) where acts as an oncoprotein E3 ligase." (PMID 36918822, 2023). "The degradation of LATS1 is important for WWP1-induced increased cell proliferation in breast cancer cells, opening a novel strategy to develop drugs targeting WWP1 for suppressing breast cancer cell growth." (PMID 35205738, 2022). "WWP1 inhibited CXCL12-induced cell migration and bone metastasis in breast cancer, while knockdown of WWP1 promoted bond metastasis of breast cancer cells." (PMID 34226507, 2021). "Both Yes-associated protein (YAP) and TAZ antagonized degradation of KLF5 by WWP1, resulting in enhancement of proliferation of breast cancer cells." (PMID 34226507, 2021). "Breast cancer patients with only nuclear-localized WWP1 in tumors had favorable prognosis compared with that with both cytoplamic and nuclear WWP1 expressions." (PMID 34226507, 2021). "Silencing of WWP1 caused cell cycle arrest and apoptotic death of MCF7 and HCC1500 breast cancer cells via activation of caspases expression." (PMID 34226507, 2021). "Previously, WWP1 was shown to be overexpressed or amplified in breast cancer, indicating that it acts as an oncogene." (PMID 33648498, 2021). "One study showed that knockdown of WWP1 elevated the expression of CXCR4 in MDA-MB-231 breast cancer cells." (PMID 34226507, 2021).
breast carcinoma (continued). "Following this line of reasoning, WWP1 is known to be overexpressed in types of prostate and breast cancer, but WWP1 also functions as an E3 ligase for several oncogenic substrates as well." (PMID 31905981, 2019). "This pro-proliferative effect of WWP1 on breast cancer is in concordance with other results that showed that WWP1 stabilizes ER, which supports cell proliferation in ER+ cells." (PMID 30619734, 2018). "Another WW domain containing E3 ligase that was shown to play a role in breast cancer migration and metastasis is WWP1." (PMID 30619734, 2018). "WWP1 knockdown in MDA-MB-231 breast cancer cells results in more osteolytic lesions and increases tumor area in bone marrow of mice when injected into the left ventricle of the heart." (PMID 30619734, 2018). "Previous studies that investigated WWP1 expression level in breast cancer revealed that WWP1 knockdown significantly induces cell growth arrest and apoptosis in breast cancer cell lines by activating different caspases." (PMID 30619734, 2018). "In breast cancer cells, Itch and WWP1 ubiquitinate Lats136, 37, which leads to an increase of non-phosphorylated YAP36." (PMID 29093443, 2017). "Studies have also revealed that WWP1 plays vital roles in the initiation, development, progression, and prognosis of numerous malignancies, including prostate cancer, breast carcinoma, hepatocellular carcinoma and GC." (PMID 28431583, 2017). "The copy number gain of WWP1 has been reported in 51% of breast cancer cell lines; 41% of primary breast tumors; 35% of oral cancer samples; 44% of prostate cancer cell lines and xenografts; and 31% of clinical prostate cancer samples." (PMID 26506518, 2015). "Negative regulation of LATS1 function was shown to mediate WWP1-induced breast cancer cell proliferation." (PMID 25350971, 2014). "Since down-regulation of LATS1 and over-expression of WWP1 was shown to be involved in the development of breast cancer, we further explored the physical and functional interaction of WWP1 and LATS1." (PMID 23573293, 2013). "Genes reported in Perou’s breast cancer intrinsic genes list, including WWP1, TECA3, and ADRM1, were also differentially expressed between ER-positive and -negative breast cancers." (PMID 24098497, 2013). "Knockdown of WWP1 in breast cancer epithelial cell lines induces growth arrest and apoptosis further supporting a role in tumorigenesis." (PMID 22629406, 2012). "Additionally, the membrane fraction of PTEN was increased in WWP1-depleted cells, consistent with observations in prostate and breast cancer cells." (PMID 39656237, 2025). "Additionally, WWP1 was found to suppress PTEN antagonism of PI3K/AKT signaling in prostate and breast cancer, and a natural potent WWP1 inhibitor I3C effectively inhibits tumorigenesis driven by the PI3K-AKT pathway." (PMID 39014007, 2024). "Taken together, our results unprecedentedly highlight a potential protective role of CYYR1 in breast cancer tumorigenesis that could be attributed to its ability to promote WWP1 autoubiquitination and degradation." (PMID 39059493, 2024). "Collectively, these observations suggest that CYYR1 downregulation in breast cancer could favor tumor progression by increasing WWP1 protein." (PMID 39059493, 2024). "Notably, inhibiting WWP1 enhances endogenous ΔNp63α levels in breast cancer, thereby conferring resistance to doxorubicin-induced apoptosis." (PMID 38129384, 2023). "This WWP1-mediated degradation of LATS1 increases cell proliferation in breast cancer cells." (PMID 34712671, 2021). "Interestingly, two studies exhibited that WWP1 has a tumor-suppressive function in glioma and breast cancer cells." (PMID 34226507, 2021). "Data from Lianping Xing group indicate that WWP1 may inhibit bone metastasis of prostate and breast cancer cells via destabilizing chemokine receptor CXCR4 as well as transcription factors Runx2 and JunB." (PMID 34712671, 2021).
breast carcinoma (continued). "WWP1 downregulation caused inhibition of ER levels in MCF7 and T47D breast cancer cells." (PMID 34226507, 2021). "WWP1 has been confirmed to act as an oncogene in a variety of cancers, including breast cancer." (PMID 33648498, 2021). "Additionally, WWP1 promoted TRAIL resistance via inhibition of caspase-8-induced apoptosis in ERα-positive breast cancer cells." (PMID 34226507, 2021). "In breast cancer cell line T47D, six isoforms of WWP1 have been identified." (PMID 30619734, 2018). "Another E3 that was connected to breast cancer cell proliferation is WWP1." (PMID 30619734, 2018). "For example, WWP1 was shown to inhibit TRAIL induced apoptosis in breast cancer cell lines." (PMID 30619734, 2018). "Previous investigations have shown that overexpression of WWP1 could promote cell growth, whereas depletion of WWP1 suppressed proliferation and induced apoptosis in breast cancer cells, prostate cancer cells and oral cancer cells." (PMID 26506518, 2015). "We have also shown that WWP1 regulates breast cancer cell proliferation by down-regulating LATS1." (PMID 23573293, 2013). "In breast cancer, it has been shown that WWP1 is an oncogene and LATS1 is a tumor suppressor gene." (PMID 23573293, 2013). "Importantly, we also showed that degradation of LATS1 is critical in mediating WWP1-induced increased cell proliferation in breast cancer cells." (PMID 23573293, 2013). "Moreover, Subik and coworkers recently reported that the ubiquitin E3 ligase WWP1 can negatively regulate cell migration to CXCL12 by limiting CXCR4 degradation to promote breast cancer metastasis to bone." (PMID 23472074, 2013). "Moreover, this group reported that cytoplasmic WWP1 expression was highly expressed in breast tumor tissues and was linked to estrogen receptor alpha (ERα) and insulin-like growth factor receptor 1 (IGF-1R) expression in breast carcinoma." (PMID 34226507, 2021). "Therefore, the role as a negative regulator of HER4 may, to some extent, account for the positive regulation of WWP1 on proliferation and survival of mammary epithelial cells, as well as tumorigenesis of breast cancer." (PMID 34712671, 2021). "Interestingly, nuclear–cytoplasmic distribution of WWP1 might predict the prognosis of breast cancer patients." (PMID 34226507, 2021). "Previous reports have suggested that WWP1 decreases the PTEN activity, which in turn deregulates the activity of the PI3K-AKT pathway in prostate and breast cancer cells." (PMID 39656237, 2025). "WWP1 promotes the ubiquitination and degradation of the oncogenic chemokine receptor CXCR4, thereby inhibiting breast cancer migration and metastasis." (PMID 40280416, 2025). "Dual inhibition of WWP1 and PI3K has shown a synergistic growth-inhibitory effect in breast cancer cells that have acquired resistance to PI3K inhibitors, provided that PTEN is not completely deleted." (PMID 39656237, 2025). "Research indicates that TAZ/YAP can counteract WWP1-mediated KLF5 degradation, thereby promoting breast cancer cell proliferation and tumor development." (PMID 39949609, 2024). "WWP1 can negatively regulate and degrade LATS1 through the 26 s proteasome pathway, resulting in increased cell proliferation in breast cancer." (PMID 38129384, 2023). "YAP and TAZ can also inhibit WWP1-mediated KLF5 degradation, leading to breast cancer proliferation (Fig. 5A3,)." (PMID 38129384, 2023). "However, the exact mechanisms by which WWP1 is associated with TRAIL resistance but not with TNFα resistance in breast cancer remain unclear and require further research." (PMID 38129384, 2023). "RNAi and overexpression studies indicate that WWP1 facilitates migration and invasion in HCC, prostate cancer, breast cancer, CRC, PTC, gastric cancer, LSCC, osteosarcoma, CSCC." (PMID 38129384, 2023). "RNAi-mediated knockdown of WWP1 induces apoptosis in oral cancer, HCC, breast cancer, osteosarcoma, gastric cancer, cutaneous squamous cell carcinoma cells and AML." (PMID 38129384, 2023).
breast carcinoma (continued). "For relapse-free survival, breast cancer patients with higher expression of VEGFA, EZH2, CASP3, WWP1, CUL2, and COL3A1 had poorer prognosis." (PMID 35812757, 2022). "WWP1-mediated ubiquitination of DVL2 initiates the WNT-PCP pathway, resulting in cell motility and breast cancer invasion/metastasis." (PMID 34712671, 2021). "In support of this study, one group also observed that WWP1 suppressed the expression of ErbB4/HER4 via ubiquitination and degradation in breast cancer." (PMID 34226507, 2021). "In summary, WWP1 govern CXCL12-mediated lysosomal degradation of CXCR4, leading to regulation of cell migration and bone metastasis in breast cancer." (PMID 34226507, 2021). "In this context, while over-expression of WWP1 enhances cell proliferation in LATS1-positive MCF10A mammary epithelial cells, knockdown of WWP1 in MCF7 breast cancer cells reduces their proliferation." (PMID 30619734, 2018). "Notably, combined treatment with WWP1 and PI3K inhibitors has demonstrated a synergistic anti-tumor effect in breast cancer cells that were resistant to PI3K inhibitors." (PMID 39656237, 2025). "WWP1 interacts with the PY motif of the oncogene MUC1 to promote its ubiquitin-mediated lysosomal degradation, thus inhibiting cell proliferation and colony formation in breast cancer, liver cancer, and non-small cell lung cancer (NSCLC)." (PMID 38129384, 2023). "Surprisingly, breast cancer patients with low or absent WWP1 expression had the worst prognosis compared with those patients with middle or high expression of WWP1." (PMID 34226507, 2021). "Moreover, WWP1 promoted LATS1 ubiquitination and degradation, leading to promoting proliferation of breast cancer cells." (PMID 34226507, 2021). "For instance, though WWP1 overexpression in mammary epithelial cell lines MCF10A and 184B5 leads to increased proliferation, knockdown of this E3 ligase promotes migration and bone metastasis of MDA-MB-231 breast cancer cells." (PMID 34712671, 2021). "WWP1 targets HER4 CYT1 for ubiquitination and degradation, thereby preventing HER4 signaling and breast tumorigenesis, which could have implications for developing therapies aimed at modulating HER4 signaling in breast cancer." (PMID 38129384, 2023). "Therefore, inhibition of WWP1 could be a promising approach for activation of LATS1 and further blocking growth of breast cancer cells." (PMID 34226507, 2021). "Moreover, a correlation was found between the expression levels of WWP1 in four breast cancer cell lines and TRAIL resistance, but not tumor necrosis factor alpha (TNFα) and doxorubicin resistance." (PMID 30619734, 2018). "Consistent with this notion, WWP1 rather than Itch is amplified and up-regulated in breast cancer." (PMID 23573293, 2013). "Since loss of WWP1 causes enhanced levels of LATS1 and decreased tumor cell growth, development of strategies that specifically target WWP1 or disrupt LATS1 and WWP1 interaction in breast cancers to activate LATS1 may be a useful approach for successful cancer therapy." (PMID 23573293, 2013). "However, knockdown WWP1 promotes cell survival in ERα‐negative breast cancer cells." (PMID 39049965, 2024). "Besides, a combination treatment by NEDD4-1 and WWP1 inducers for melanoma cancer, NEDD4-1 and ITCH inhibitors for prostate cancer, NEDD4-1 and SMURF1 for the HCC, as well as SMURF2 inducers and ITCH inhibitors for the breast cancer can be considered as the effective therapeutic approaches." (PMID 36918822, 2023).